VCPIP1 (valosin containing protein interacting protein 1)
Description:
Deubiquitinating enzyme involved in DNA repair and reassembly of the Golgi apparatus and the endoplasmic reticulum following mitosis. Necessary for VCP-mediated reassembly of Golgi stacks after mitosis (By similarity). Plays a role in VCP-mediated formation of transitional endoplasmic reticulum (tER) (By similarity). Mediates dissociation of the ternary complex containing STX5A, NSFL1C and VCP (By similarity). Also involved in DNA repair following phosphorylation by ATM or ATR: acts by catalyzing deubiquitination of SPRTN, thereby promoting SPRTN recruitment to chromatin and subsequent proteolytic cleavage of covalent DNA-protein cross-links (DPCs). Hydrolyzes 'Lys-11'- and 'Lys-48'-linked polyubiquitin chains. (Microbial infection) Regulates the duration of C.botulinum neurotoxin type A (BoNT/A) intoxication by catalyzing deubiquitination of Botulinum neurotoxin A light chain (LC), thereby preventing LC degradation by the proteasome, and accelerating botulinum neurotoxin intoxication in patients.
Synonyms: KIAA1850; VCIP135; FLJ23132; DUBA3
Tractability: PROTAC: ubiquitination databases record sites on it; its protein half-life has been measured.
Target class: Enzyme; Hydrolase
Gene: Protein-coding gene on chromosome 8 (66,628,487 to 66,667,231, reverse strand). Ensembl gene ENSG00000175073.
Subcellular location: Nucleus; Cytoplasm; Endoplasmic reticulum; Golgi apparatus, Golgi stack
Subcellular location (Human Protein Atlas): Plasma membrane; Centrosome; Cytosol
Pathways (Reactome):
Metabolism of proteins: Ovarian tumor domain proteases
Gene Ontology:
Molecular function: cysteine-type deubiquitinase activity; protein binding; catalytic activity
Biological process: DNA damage response; protein deubiquitination; protein K11-linked deubiquitination; protein K48-linked deubiquitination; protein-DNA covalent cross-linking repair; regulation of protein localization to chromatin; endoplasmic reticulum membrane fusion; Golgi reassembly; protein ubiquitination; protein unfolding; Golgi organization
Cellular component: cytoplasm; cytosol; nucleus; ATPase complex; endoplasmic reticulum; endoplasmic reticulum lumen; Golgi stack
Genetic constraint (gnomAD): Loss-of-function variants: 7 observed, 83.4 expected, observed/expected ratio (o/e) 0.0839, 90% interval 0.047 to 0.16. The upper end of that interval is the gene's LOEUF score, 0.16, which puts it in group 1 of 6, group 1 being the genes least tolerant of losing a copy. Missense variants: 1,053 observed, 1,540.5 expected, observed/expected ratio (o/e) 0.68, 90% interval 0.65 to 0.72. Synonymous variants: 534 observed, 570.62 expected, observed/expected ratio (o/e) 0.94, 90% interval 0.87 to 1.
Homologues: Orthologues: chimpanzee VCPIP1 (99% identical), macaque VCPIP1 (99% identical), dog VCPIP1 (97% identical), pig VCPIP1 (97% identical), rabbit VCPIP1 (96% identical), rat Vcpip1 (96% identical), mouse Vcpip1 (95% identical), guinea pig VCPIP1 (95% identical), tropical clawed frog vcpip1 (77% identical), zebrafish vcpip1 (65% identical).
Diseases named in the same sentence as VCPIP1 in open-access papers:
VCPIP1 is named in the same sentence as 17 diseases in open-access papers, as found by Europe PMC text mining. Sharing a sentence is not in itself a finding about the gene and the disease. The quoted sentences say what the papers report.
breast carcinoma (2 papers, 2020 to 2024). "For instance, increased expression levels of OTUD6B, UCH37, VCPIP1, USP7, and COPS5 have been detected in various breast cancers." (PMID 33070427, 2020).
salivary gland tumors (2 papers, 2024). "In contrast, other than the identification of a MYBL1-VCPIP1 gene fusion event in salivary gland tumors, a possible relationship between MYBL1 and VCPIP1 genes has not been established." (PMID 39796135, 2024). "Related to other cancers, MYBL1/VCPIP1 gene fusions were detected in salivary gland tumors supporting a documented relationship between the two genes." (PMID 38473786, 2024). "Other than the fact that MYBL1 and VCPIP1 genes are associated with cell cycle signaling events and a MYBL1-VCPIP1 fusion product has been observed in salivary gland tumors, no experimental data support a relationship between the two genes." (PMID 39796135, 2024).
hepatoma (1 paper, 2022). "Functionally, HBx specifically binding to VCPIP1 significantly enhanced the transcriptional transactivation of HBx by activating NF-κB, AP-1, and SP-1 and inhibited hepatoma cell clonogenicity in Huh7 and HepG2 cells." (PMID 35695579, 2022). "Whether VCPIP1 affected the HBx protein stability in the context of HBV infection was tested ultimately in the HepG2-NTCP-reconstituted hepatoma cells infected with HBV particles harvested from HepAD38 cells." (PMID 35695579, 2022). "Furthermore, VCPIP1-HBx interaction appears to facilitate HBx protein to exert its pleiotropic effects including canonical transactivational activity and cell proliferation inhibition, suggesting its potential role in the pathogenesis of HBV-related hepatocellular carcinoma." (PMID 35695579, 2022).
ovarian tumor (1 paper, 2022). "Based on the yeast two-hybrid assay, a critical member in the ovarian tumor (OTU) protease class of DUBs, valosin-containing protein-interacting protein 1 (VCPIP1), was identified as a potential interacting molecule of HBx." (PMID 35695579, 2022).
pancreatic adenocarcinoma (1 paper, 2025). "Targeting VCPIP1 pharmaceutically via CAS inhibited the progression of PAAD and enhanced sensitivity to GEM treatment, suggesting that blocking VCPIP1 might be a viable strategy for treating Hippo-driven pancreatic adenocarcinoma." (PMID 40436845, 2025). "Therefore, blocking VCPIP1 could be a plausible strategy for treating YAP-driven pancreatic adenocarcinoma." (PMID 40436845, 2025).
pancreatic cancer (1 paper, 2025). "In general, our study revealed an unexpected positive feedback loop between VCPIP1 and Hippo signaling in pancreatic cancer." (PMID 40436845, 2025). "We also revealed that VCPIP1 was correlated with YAP expression and poor survival in specimens from patients with pancreatic cancer." (PMID 40436845, 2025).
triple-negative breast carcinoma (1 paper, 2024). An invasive breast carcinoma which is negative for expression of estrogen receptor (ER), progesterone receptor (PR), and human epidermal growth factor receptor 2 (HER2). "In addition, MYBL1 and VCPIP1 genes are co-expressed and dysregulated in some of the same triple negative breast cancer patient samples." (PMID 39796135, 2024).
viral infectious disease (1 paper, 2022). Any disease caused by a virus. "Overall, VCPIP1 is a new DUB for HBx protein stability but not via deubiquitination, thereby broadening knowledge of the pathogenic involvement of the DUB family in viral infectious diseases." (PMID 35695579, 2022).
tumor (5 papers, 2022 to 2024). "While high expression of VCPIP1 was associated with worse survival in the Cavalli dataset, expression of VCPIP1 in none of the four MB groups was significantly higher than in non-tumor tissues in the Swartling dataset." (PMID 37892185, 2023). "The VCPIP1 protein levels were also included in these analyses to show over-expression of the protein in TNBC compared to non-tumor breast cells." (PMID 39796135, 2024). "MYBL1, VCPIP1, MYC and BOP1 transcript expression levels were assessed in MCF10A non-tumor triple negative cell lines compared to Hs 578T, BT-549 and MDA-MB-231 TNBC cell lines." (PMID 38473786, 2024). "The transcriptional regulation of VCPIP1 by the MYBL1 gene could implicate MYBL1 in these processes, which might contribute to tumor processes in TNBC." (PMID 39796135, 2024).
cancer (4 papers, 2014 to 2025). A tumor composed of atypical neoplastic, often pleomorphic cells that invade other tissues. "Additionally, dysregulation of Vcpip1 has been identified as mutated in 2% of cancers, including large intestine, skin, and urinary tract." (PMID 25474466, 2014). "Next, we analyzed VCPIP1 expression using combined GETx and TCGA databases and found that the expression of VCPIP1 was elevated in PAAD as well as in several other TCGA cancer types." (PMID 40436845, 2025). "The DUB family of genes is being considered as therapeutic targets for cancer; hence, VCPIP1 is an interesting candidate to examine for its possible involvement in TNBC." (PMID 38473786, 2024). "Since YAP and TAZ have partially overlapping and partially distinct functions in cancer, we set out to validate whether VCPIP1 also have a regulatory effect on TAZ protein." (PMID 40436845, 2025).
infection (1 paper, 2024). The state of being infected such as from the introduction of a foreign agent such as serum, vaccine, antigenic substance or organism. "By using a series of HBV replication and infection models, we extensively characterized VCPIP1-mediated upregulation of HBV transcription, antigen expression, and genome replication." (PMID 39494904, 2024). "VCPIP1-mediated upregulation of HBV transcription, antigen expression, and genome replication was demonstrated using a series of HBV replication and infection models." (PMID 39494904, 2024). "Knockdown of endogenous VCPIP1 expression in HepG2-NTCP cells resulted in slower production of secreted HBeAg post-infection and reduced viral transcription and progeny virus production at 7 days post-infection." (PMID 39494904, 2024).
VCPIP1 also shares sentences with these, for which no sentence is quoted: Breast Invasive Carcinoma (1 paper); cervical squamous cell carcinoma (1); liver cancer (1); lung adenocarcinoma (1); thyroid carcinoma (1); uterine corpus endometrial carcinoma (1).